KRAS (KRas proto-oncogene, GTPase)
Diseases named in the same sentence as KRAS in open-access papers (continued):
Sharing a sentence is not in itself a finding about the gene and the disease.
cancer (continued). "We found that KRAS and PDE6D relative levels are widelyvariable among different cell types, with the highest levels of bothproteins in human cancer cells (A549, H358, and H2009) and their lowestlevels in retinal retinal pigmented epithelial (RPE) cells." (PMID 35104933, 2022). "Therefore, the KRAS mutations in our clinical PDAC samples were verified in-house by Sanger sequencing, and analysis of the samples by immunohistochemistry (IHC) showed an increase in microlymphatic vessels in the KRASG12D PDAC tissues as compared with cancer tissues with other KRAS subtypes." (PMID 35579947, 2022). "Recent studies have shown successful treatments using neoantigen-based shared cancer vaccines in some types of cancers such as IDH1 R132H for glioblastoma and KRAS G12D for colon cancer." (PMID 36298462, 2022). "For example, G4s were shown to modulate the expression of key cancer genes, such as MYC, c-Kit, BCL2, and KRAS, with their disruption resulting in pronounced expression changes." (PMID 35573091, 2022). "BCL6 expression was increased upon KRAS activation in lung tumor tissue in mice and was positively correlated with the expression of KRAS-GTP, the active form of KRAS, in various human cancer cell lines." (PMID 36377663, 2022). "For example, cancer-cell-derived EVs carry pro-tumorigenic proteins such as growth factors (mutant EGFR) and oncogenes (e.g., KRAS)." (PMID 36139610, 2022). "The present review will focus on the various mechanisms of CREB-dependent EMP, downstream of mutant KRAS in PDAC and other cancer types." (PMID 35800049, 2022). "By contrast, in vitro studies have identified alterations in MYC, mTOR, and PIK3CA, but notably rarely KRAS alterations, as potential drivers of resistance in MET-addicted cancer cells with MET-amp." (PMID 35326531, 2022). "An overall assessment of the performance of the pan-cancer samples for all the source materials tested in this study was a maximum of 100% for BRAF; 98% for KRAS, and 94% for the GeneFusion Assays." (PMID 36293374, 2022). "We found that CD44, CDK6, GATA4, GATA6, KLF5, and KRAS, which were amplified in TCGA STAD cohort, were amplified in cancer cell clusters." (PMID 35087207, 2022). "The ability of SBT-100 to penetrate the cell membrane and bind intracellular KRAS and STAT3 translates into functional suppression of cancer growth and proliferation in vitro and in vivo." (PMID 35886918, 2022). "Except for inhibitors targeting nonkinase cellular proteins (e.g., mutated KRAS and proteasome) or epigenetic modulators (e.g., histone deacetylases), most SMKIs suppress protein kinases involved in the transformation, growth, proliferation, and survival of cancer cells." (PMID 36224343, 2022). "Mutant KRAS is essential for PDAC tumorigenesis and growth establishing PDAC as the most RAS-addicted cancer." (PMID 36048281, 2022).
cancer (continued). "AMG510, the first drug for KRAS approved by FDA, covalently binds to Cys12 in the KRASG12C protein and has shown promising anti-cancer activity in clinical trials." (PMID 36033504, 2022). "We previously demonstrated the efficacy of the PPRH approach on the KRAS and TYMS genes, and the modulation of their expression resulted in a reduction in cancer cell viability." (PMID 36613820, 2022). "One prominent resistance mechanism to EGFR‐TKIs, KRAS, or MEK inhibitors is the reactivation of ERK1/2 signaling, which can drive cancer cell survival and proliferation." (PMID 35838331, 2022). "Kyoto encyclopedia of genes and genomes (KEGG) analysis showed that hsa_circ_0004099 was enriched in several cancer pathways, which were collectively enriched in four genes namely TCF7L2, NRAS, CTNNB1, and KRAS." (PMID 36399471, 2022). "Overexpressing GLUT1 in KRAS and BRAF mutant cells reportedly results in massive DHA uptake, ultimately leading to ROS production and cancer cell death." (PMID 35915609, 2022). "GSEA analysis results demonstrated that multiple cancer-related pathways (such as G2M checkpoint, MYC targets, E2F targets, and KRAS) were upregulated for LIHC with high RPPF19 expression." (PMID 35252202, 2022). "We finally present an overview of genetically engineered mouse models bearing KRAS and RAS-MAPK pathway aberrations in the hematopoietic compartment, which are valuable tools in the understanding of cancer biology and etiology." (PMID 35158933, 2022). "Numerous combination trials with KRAS and other MAPK pathway (SHP2/MEK/ERK) inhibitors are in progress aimed at improving outcomes in patients with KRASm cancers and exploiting the presence of targetable co-alterations." (PMID 36494601, 2022). "In this study, we investigated the connection between novel emerged KRAS-G12C inhibitor, ARS-1620, and ABCB1-overexpressing cancer cells." (PMID 35281897, 2022). "Secondly, GSEA indicated that KCDEGs were enriched in several cancer hallmarks such as EMT, MYC targets, KRAS signaling, and inflammatory response." (PMID 35479936, 2022). "Interestingly, in two patients carrying RAD21 p.P298S/A we identified a known pathogenic KRAS hot-spot mutation as a common somatic denominator in the respective tumors, which is in line with a recently published association between cohesin complex mutations and RAS signaling in cancer progression." (PMID 35563565, 2022). "RTK activation upregulates SHP2 phosphorylation and accelerates the progress from GDP-bound KRAS to GTP-bound KRAS, which enables cancer cells to escape the blockade of KRASG12C." (PMID 35053550, 2022). "However, either cancer cells under glucose deprivation, hypoxia, or oncogenic KRAS mutation or nontumorigenic pancreatic cells under high glucose levels cause hyper-O-GlcNAcylation of cellular proteins, challenging the regulation of O-GlcNAcylation via the versatile UDP-GlcNAc." (PMID 36151074, 2022).
cancer (continued). "Homozygous deletions of KRAS are the most frequent genetic alteration in pancreatic epithelial adenocarcinoma (PDAC), which results in cell metastasis and the transformation of cancer tumors." (PMID 36330448, 2022). "PPI analysis showed potential interactions between three cancer driver genes (AKT1, KRAS, and PIK3CA) and candidate genes (CCNE2, RAD51, and NEIL3)." (PMID 36233194, 2022). "Here, a cancer cell targeting strategy is provided for PDAC, engaging the demonstrated KRAS-responsive delivery carrier 70 kDa dextran." (PMID 35154474, 2022). "Moreover, a down-regulation of feature “variance” was observed in ALK-translocated (n = 2) vs wild-type (n = 109) cancers (4.60 vs 8.64; p = 0.0282), but there was no differentially expressed features regarding KRAS-mutated (n = 27) vs wild-type (n = 88) cancers." (PMID 35482262, 2022). "Generally, RUNX3 is known to elicit its tumor-suppressive ability through major cancer signaling pathways including TGF-β, Wnt/β-catenin, and KRAS." (PMID 35898303, 2022). "While nearly 85% of RAS-driven cancers are KRAS mutants, HRAS and NRAS share approximately 82% to 90% of the amino acid (aa) sequence with KRAS, with the majority of variance occurring within the C-terminal region." (PMID 35923912, 2022). "For example, let-7a suppresses cancer progression by decreasing the levels of HMGA2 or RAS family members (e.g., KRAS)." (PMID 35663957, 2022). "With several more clinical trials underway e.g., JDQ-443/NCT04699188, mesenchymal stromal cells-derived exosomes with KRAS G12D siRNA/NCT03608631 and anti-KRAS G12V mTCR PBL/NCT03190941), a new era seems to be emerging for cancer treatment." (PMID 35158934, 2022). "Spikes in cfDNA or changes in the KRAS mutation status of ctDNA may be predictive of the success of treatment in resectable PDAC patients undergoing neoadjuvant therapy and are associated with effective anti-cancer treatments resulting in cellular material dissemination." (PMID 35448266, 2022). "For cancer signaling, MTORC1 and PI3K-AKT-MTOR pathway were significantly enriched in the high-m7Gscore group, while KRAS and hypoxia pathways were enriched in the low-m7Gscore group." (PMID 36339001, 2022). "The mutational analysis highlighted the likely importance of NRAS, KRAS, JAK2, and CREBBP in pediatric cancer development because these genes are the most commonly mutated genes in pediatric cancer patients." (PMID 36497424, 2022). "The results we describe here emphasize the SII-P as a privileged drug-binding site on KRAS and unveil new therapeutic opportunities in RAS-driven cancer." (PMID 35314814, 2022). "Recently, it has suggested that mast cells (MCs), microRNAs (miRNAs), Kirsten rat sarcoma (KRAS) and v-raf murine sarcoma viral oncogene homologue B (BRAF) plat a role in cancer growth and progression." (PMID 34680251, 2021). "The combination of KRAS G12C inhibitors (AMG510 or MRTX849) alongside a clinical‐stage small molecule FAK inhibitor IN10018 produced encouraging anti‐cancer effects against multiple cancer cell lines, CDX, and PDX models of KRAS G12C mutant cancers." (PMID 34151545, 2021). "CDK4/6is, Palbociclib, Ribociclib and Abemaciclib, have been effectively used in combination therapy, and have shown to be synergistic with drugs targeting other oncogenic pathways, including MEK, KRAS, BRAF, and ALK, in various cancers." (PMID 34138895, 2021).
cancer (continued). "Further visualizing the important cancer-related pathways, we found that cluster 2 had more EMT, KRAS and TNF signaling pathways, which was consistent with the worse prognosis associated with this cluster." (PMID 33973529, 2021). "The most dysregulated genes were related with the signaling pathways such as AKT-MTOR, CYCLIN D1, KRAS, EIF4E, RB, and ATM, which play an essential role in cancer cell proliferation, survival, and response to external stimuli." (PMID 34944712, 2021). "Targeting KRAS or downstream effectors, such as p-ERK, has been a goal for many years in the cancer research field with recent progress made with MAPK inhibitors and more recently with KRAS G12C inhibitors." (PMID 34638488, 2021). "Unspecific, broad toxicity against KRAS (MDA-MB-231, MIA PaCa-2) and HRAS mutant (Hs 578T, T24) cancer cell lines, as well as HEK293-EBNA cells, is a major issue of OphA." (PMID 34307350, 2021). "While cancer cells consume glutamine at exceedingly high rates to meet their energetic and biosynthetic requirements for proliferation, it is not clear yet whether oncogenic KRAS mutations influence glutamine transport." (PMID 34003553, 2021). "The authors explained these growth changes of MIA Pa-Ca-2 and EAC tumors by the reduced expression of the KRAS and BCL2 genes in cancer cells." (PMID 33632214, 2021). "This locks KRAS in a GTP-bound, active state and promotes cancer cell growth and apoptosis resistance." (PMID 33809660, 2021). "Therefore, the down-regulation of KRAS could delay cancer progression and benefit immunotherapy." (PMID 33708243, 2021). "The downstream genes of DDX3X-SP1-mediated transactivation include P21, KRAS, and MDM2, which are critical for cancer development and progression." (PMID 33627125, 2021). "Activating mutants of RAS are commonly found in human cancers, but to date selective targeting of RAS in the clinic has been limited to KRAS(G12C) through covalent inhibitors." (PMID 33976200, 2021). "The selectivity and potency of 12VC1 allowed us to perform proof-of-concept evaluation on whether a mutant-selective, noncovalent reagent can effectively inhibit the growth of cancer cells driven by endogenous KRAS mutants by using monobodies as genetically encoded, intracellular reagents." (PMID 33976200, 2021). "Based on these results, cell-based ELISA assay further confirmed the binding specificity of mHALT-1-scFv immunotoxin towards G12V KRAS SW-480 and G13D KRAS HCT 116 cancer cells." (PMID 33959410, 2021). "Based on the Genomics of Drug Sensitivity in Cancer (GDSC) data, similar trends were also observed, for the same KRAS mutant cell lines, with the MEK and ERK inhibitors Trametinib, ERK-6604, ERK-2440 and Ulixertinib." (PMID 34573384, 2021). "Collectively, our data reveal that oncogenic KRAS alters the expression of AATs such as SLC1A5/ASCT2, SLC7A5/LAT1, and SLC38A2/SNAT2 and thereby increase the uptake of AAs to support cancer cell proliferation through mTOR activation." (PMID 34003553, 2021). "Overall, the RAS family constitutes 36 human genes, but KRAS, HRAS, and NRAS by far are the most prominent ones involved in human cancer." (PMID 34944853, 2021). "The KRAS gene is a member of the RAS family of oncogenes and the well-studied superfamily of small GTPases in cancers." (PMID 34571724, 2021). "These approaches identified several oncogenes, including KRAS, CREBBP, PTEN, and BRCA2, as SDL genetic partners of EXT1, highlighting its potential clinical relevance in different cancers." (PMID 33962942, 2021). "miRNAs play direct or indirect roles in regulating oncogenes (KRAS), tumor suppressor genes (FHIT, WWOX), and immune-related gene (TLR8), which ultimately promote cancer cell growth and dissemination." (PMID 34470640, 2021).
cancer (continued). "Enrichment analysis showed that ISM1 upregulation was positively correlated with cancer-related pathways, such as EMT, hypoxia, and the Notch and KRAS signaling pathways." (PMID 34350177, 2021). "Recently, it has been shown that pharmacologic ascorbate impairs the Warburg effect in KRAS mutant cells and xenografts by resulting in the downregulation of both GLUT1- and PKM2-dependent protein expression, suggesting its positive role in cancer therapies." (PMID 33925206, 2021). "It has been shown that the oxidized form of vitamin C is structurally similar to glucose and is efficiently taken up via GLUT1 transporters by highly glycolytic cancer cells, such as BRAF or KRAS mutant CRC cells." (PMID 34207603, 2021). "EGFR/BRAF, EFRF/KRAS, KRAS/ERBB2 demonstrated a mutually exclusive relationship, consistent with the recent evidence from cancer genomic studies which demonstrated that driver genes are often mutated in a mutually exclusive manner." (PMID 35186718, 2021). "The RAS oncogene family is comprised of three members, KRAS, NRAS, and HRAS, and plays an important role in normal development, but also for cancer development." (PMID 35048068, 2021). "Furthermore, if the CCK-BR-targeted NP can also deliver gastrin siRNA or other payloads to the PanIN lesions such as siRNA for mutant KRAS, these NPs would have the potential not only to identify but also to also treat these PanIN lesions to decrease proliferation and halt the progression to cancer." (PMID 34944412, 2021). "The anti-cancer effects of miR-193a-3p are precluded by the repression of multiple target genes, including cancer related genes such as CCND1, KRAS, RASSF1, STMN1, and MCL1." (PMID 33747358, 2021). "KRAS and the long noncoding RNA gene CTC-297 N7.11 have a similar impact across multiple cancer types." (PMID 33094325, 2021). "The apparent antagonism between mutant KRAS and induction of EMT was of particular interest, considering that KRAS mutant cancers are either dependent on KRAS or gain various degrees of KRAS independence through TGF-beta signaling." (PMID 33674596, 2021). "The inhibition of HSP90, highly expressed in most cancers, in combination with a MEK inhibitor has been identified as a promising therapeutic strategy for KRAS-mutant NSCLC." (PMID 34946644, 2021). "Interestingly, KRAS mutant cancer cells that are dependent or addicted to the KRAS oncogene are more likely to be associated with an epithelial phenotype, while those that are independent of KRAS adopt a mesenchymal phenotype." (PMID 33874986, 2021). "Overexpression of SLC7A11 was detected in KRAS-mutant lung adenocarcinoma (LUAD) and positively correlated with cancer progression." (PMID 34722530, 2021). "Two genes—KRAS proto-oncogene, GTPase homolog (KRAS) (1.46%) and adenoma polyposis coli regulator of WNT signaling pathway (APC) (1.60%) contribute the most cancer predictions." (PMID 34032581, 2021). "Evidence for LOH as a frequent event in cancer initiation has been observed in model systems for all three RAS genes (HRAS, NRAS, KRAS)." (PMID 33924994, 2021). "Anti-proliferative activities of the fourteen GNF-7 derivatives on cancer cells harboring mtRAS (H358, AsPC-1, DU-145, SW480, HCT-116, MDA-MB-231, HT-29, OCI-AML3) and KRAS, NRAS-wt (U937 and MDA-MB-468) cells." (PMID 34956887, 2021). "The mRNA expression of KRAS, BRAF, and KIT in various types of cancer from TCGA samples were analyzed using the UALCAN database (Figure A1 and Figure A2 in Appendix A)." (PMID 34769348, 2021).